CDK5 (cyclin dependent kinase 5)
Diseases named in the same sentence as CDK5 in open-access papers (continued):
Sharing a sentence is not in itself a finding about the gene and the disease.
cancer (continued). "While the prevalence of this unconventional pairing remains to be elucidated, this finding is particularly notable as it raises the possibility that in the proliferative environment of cancer cells, Cdk5 can be repurposed to form functional complexes with classical cell cycle machinery." (PMID 41369365, 2025). "Moreover, Cyclin-Dependent Kinase 5 (CDK5), involved in cytoskeletal dynamics, cancer cell migration and invasion was among the suppressed kinases." (PMID 39833546, 2025). "CDK5 can function as either an oncogene or a tumor suppressor, depending on the type of cancer." (PMID 39800748, 2025). "In parallel, Cdk5 acts within the cancer cells themselves to regulate a pro-angiogenic secretome." (PMID 41369365, 2025). "In contrast, its oncogenic potential is fully realized by hyperactive Cdk5 in some cancer types." (PMID 41369365, 2025). "Of note, both hydrophilic and lipophilic statins can inhibit Cdk5 in cancer cell line." (PMID 38842132, 2024). "Fenofibrate reduces cancer metastasis by inhibiting Cdk5 signalling." (PMID 38842132, 2024). "On the other hand, Cdk5 is also generally dysregulated in various cancer cells, and, importantly, the Rb protein is a downstream target of Cdk5 in neuroendocrine thyroid cancer." (PMID 38233717, 2024). "Inhibiting CDK5 has shown potential in suppressing cancer development." (PMID 37887415, 2023). "Here, however, we focused on targeting CDK5 in the context of cancer cells." (PMID 37760412, 2023). "CDK5 has emerged as a critical player in both cancer and neurodegenerative diseases." (PMID 37993880, 2023). "GSTP1 is also found to be a CDK5 regulator in various cancer cell lines." (PMID 37993880, 2023). "Additionally, CDK5 has been found to be activated in cancer cells or tissues upon exposure to conventional DNA-damaging therapies such as genotoxic agents." (PMID 37511490, 2023). "This review focuses on the role of CDK5 outside of the CNS, with particular emphasis on cancer." (PMID 37993880, 2023). "Similar to other cancers, CDK5 enhances both proliferation and metastasis in CRC." (PMID 37993880, 2023). "However, recently, CDK5 was reported to phosphorylate the retinoblastoma protein (Rb), promoting cancer cell proliferation." (PMID 37511490, 2023). "Other predicted dysregulated upstream STKs, checkpoint kinase 1 (CHK1) and cyclin-dependent kinase 5 (CDK5), play roles in cell cycle regulation, and their functional aberrations have been linked to diseases such as cancers (Kastan & Bartek 2004, Sharma & Sicinski 2020)." (PMID 36409629, 2023). "Yet, a role for CDK5/p35 in NK cells has not been previously reported, nor has CDK5/p35 been linked to the negative regulation of immune cell–mediated cytotoxicity against cancer cells." (PMID 37377891, 2023). "As a result, directing it to a different subcellular location using small molecules could be a promising approach to treat cancer, analogous to neuronal death triggered by nuclear CDK5." (PMID 37993880, 2023). "However, our and other studies provide evidence that CDK5 exerts anti-tumor effects in various human cancers." (PMID 37990321, 2023). "The subcellular location of the activator may be the main determinant of CDK5’s oncogenic or anti-oncogenic behaviors in some cancer cells, in which CDK5 resides both in the cytoplasm and nuclear compartments." (PMID 37993880, 2023). "Upregulation of CDK5 and/or its activator p35 in neurons promotes healthy neuronal functions, but their overexpression in nonneuronal tissues is causally linked to cancer of many origins." (PMID 37993880, 2023). "Additionally, there is growing evidence that Cdk5 plays a role in T cell activation and cancer biology." (PMID 35203613, 2022). "Given that CDK5 expression is dispensable in these cells, whereas CDK1, 2, 7, and 9 are common essential genes required for the proliferation of almost all cancer cells lines, the effects of Roscovitine are highly likely to be attributable to inhibition of CDK5." (PMID 35514210, 2022).
cancer (continued). "Considering the proteolytic role of S75 phosphorylation, this may suggest a role in antagonizing Src activity in some Cdk5-expressing cancer cell lines." (PMID 35216357, 2022). "Cyclin-dependent kinase (Cdk5) silencing primarily affects the vascular adhesion of cancer cells." (PMID 35158914, 2022). "However, the S-nitrosylation of CDK5 involved in tumorigenesis remains to be studied, thus it is interesting to investigate the role of SNO-CDK5 in cancer development." (PMID 35006426, 2021). "Increasing studies showed that CDK5 plays an important role in cancer progress." (PMID 35006426, 2021). "In addition to the role of CDK5 in the CNS, CDK5 has been reported to play essential roles in cancer progression." (PMID 34207842, 2021). "In this regard, specifically targeting PTMs on CDK5 may be a promising strategy for cancer treatment." (PMID 35006426, 2021). "Cdk5 contributes to tumorigenesis in various types of cancer." (PMID 34814918, 2021). "Since several studies have reported that RET activates STAT3 in different types of cancer, CDK5-mediated STAT3 activation with GDNF treatment remains unknown in this study." (PMID 34207842, 2021). "In addition, Noxa is constitutively expressed in cancer cells, and the CDK5 overexpression can promote the Noxa transfer from cytoplasm to mitochondria, participating in glucose metabolism to provide energy for nucleotide synthesis." (PMID 35006426, 2021). "On the basis of the newly identified regulatory signaling pathways of CDK5 related to PTMs, researchers have investigated the cancer therapeutic potential of chemical compounds, small-molecule inhibitors, and competitive peptides by targeting CDK5 and its PTMs." (PMID 35006426, 2021). "CDK5 is considered to be an atypical member of the CDKs, and its abnormal expression is involved in a variety of diseases, such as neurodegenerative diseases and cancer." (PMID 35006426, 2021). "Regarding the functional role of the acetylation modification of CDK5 in neurological diseases, and whether CDK5 also plays a similar role in the development of cancer require further investigations." (PMID 35006426, 2021). "It seems that targeting these PTM modifiers directly or indirectly could be a promising strategy for the inhibition of CDK5 activity and thus for the chemoprevention of cancer." (PMID 35006426, 2021). "Cdk5 protein kinase has been proposed as a major player in cancer progression." (PMID 34680167, 2021). "Though CDK5 is an atypical member of the cyclin-dependent kinase family, its aberrant expression links to cell proliferation, DNA damage response, apoptosis, migration and angiogenesis in cancer." (PMID 35006426, 2021). "For CDK5-mediated phosphorylation events, its substrates are involved in a variety of biological processes regulation and are closely related to the occurrence and development of cancer." (PMID 35006426, 2021). "Taken together, CDK5 is also a potential target for inhibiting angiogenesis in cancer therapy." (PMID 35006426, 2021). "According to these findings, CDK5 is a crucial regulator of cancer cell proliferation and survival." (PMID 33396266, 2020). "Also, we add the effects of CDK5 on cancer-nerve connection since nerve contribution can be one of the emerging TME." (PMID 33396266, 2020). "Furthermore, NFKB1 and HIF1 expression were negatively correlated with CDK5 and TXN2 in all three cancers, while HIF1-NFKB1 showed a positive association with each other." (PMID 32033319, 2020). "We have presented a summary of CDK5 as a biomarker and a new target in cancer treatment." (PMID 33396266, 2020). "However, more recently, in pathological conditions such as cancer, CDK5 was reported to phosphorylate the retinoblastoma protein (Rb), promoting cancer cell proliferation." (PMID 32708903, 2020).
cancer (continued). "Since the research results on inhibitors of CDK5 have been conducted to develop therapeutics for neurological diseases, if these results can be used to develop therapeutics for various cancers, it is expected to create a specific inhibitor for CDK5 at a relatively rapid pace." (PMID 33396266, 2020). "Aberrant CDK5 activation triggers tumour progression in numerous types of cancer." (PMID 33396266, 2020). "Therefore, CDK5 seems to be able to promote cancer progression through its role in the nerves surrounding the tumour in addition to its role in cancer cells, and further research is needed." (PMID 33396266, 2020). "This suggests that CDK5 can be involved in nerve fibres-mediated cancers." (PMID 33396266, 2020). "CDK5 downregulation marginally attenuated the migration of these cancers." (PMID 33396266, 2020). "This suggests that CDK5 can regulate inflammation factors conducive to the development of cancer." (PMID 33396266, 2020). "Among the hallmarks of cancer, inducing angiogenesis, tumour-promoting inflammation, and the blockade of immune destruction are associated with the TME, and we describe the effects of CDK5 on these hallmarks." (PMID 33396266, 2020). "There is much research regarding the effect of CDK5 on cancer hallmarks." (PMID 33396266, 2020). "In summary, these reports suggested that CDK5 may play important roles in resistance to DNA-damaging anti-cancer-therapies such as chemotherapy, IR or PARP inhibitors." (PMID 32708903, 2020). "Therefore, among the several findings that have been studied in neurons, for example, the roles of CDK5 related to the reorganisation of cytoskeletons, including microtubules, are likely to apply to cancer research." (PMID 33396266, 2020). "In this review, we summarise the role of CDK5 in cancer and neurons and CDK5 inhibitors." (PMID 33396266, 2020). "The relevant combination of CDK5 inhibitors with conventional DNA-damaging agents may improve anti-cancer efficacy." (PMID 32708903, 2020). "Aberrant expression or hyperactivation of this kinase contributes to tumorigenesis and progression of several tumors including cancer stem cells by stimulating proliferation, migration, angiogenesis, and CDK5 activity regulates the DNA damage pathway, chemotherapy resistance and anti-tumor immunity." (PMID 32974274, 2020). "The role of CDK5 in cancer cell survival remains unclear, with some groups reporting that CDK5 prevents while others proposing that CDK5 promotes apoptosis." (PMID 31910742, 2020). "Indeed, inhibition of CDK5 kinase activity or depletion of CDK5 using siRNAs increased sensitivity of cancer cells to DNA damaging agents." (PMID 31910742, 2020). "There is increasing evidence that CDK5 may play a role in the initiation of DNA damage response (DDR) in cancer cells." (PMID 31910742, 2020). "Hence, the inhibition of migration factors by suppressing the CDK5 signalling pathway is an attractive strategy for preventing cancer invasion." (PMID 33396266, 2020). "The function of CDK5 in cancer cell proliferation remains controversial." (PMID 31910742, 2020). "Recently, evidence has shown the involvement of CDK5 in cancer." (PMID 33396266, 2020). "Recently, CDK5 has been proposed to play a vital role in cancer development, and the overexpression of CDK5 correlates with poor prognosis, tumour proliferation, migration, and invasion in a variety of cancers." (PMID 33396266, 2020). "Although there is not much evidence showing the association between CDK5 and cancer via neurotransmitters, this can be a potential target for cancer treatment." (PMID 33396266, 2020). "Hence, the role of CDK5 in promoting or inhibiting cancer cell migration remains controversial and requires further studies." (PMID 31910742, 2020). "In addition, a growing number of studies describe upregulation or hyperactivation of CDK5 in human cancers, indicating that CDK5 constitutes a relevant target in oncology." (PMID 32974274, 2020).
cancer (continued). "Also, we introduced representative CDK5 inhibitors and suggested the possibility of CDK5 inhibitors as treatments for refractory cancer." (PMID 33396266, 2020). "Although Cdk5 is highly activated in cancer, its function is still elusive." (PMID 30911317, 2019). "CDK5 prohibits DNA damage with STAT3 interaction in cancer cells." (PMID 31395805, 2019). "Although it is known that USF2 is a phosphoprotein and that CDK5 has an abnormal expression and activity in several human cancers, it is unknown whether USF2 is a substrate for CDK5." (PMID 31013770, 2019). "CDK5 regulated by p35 or p25 may trigger many different types of biological responses, including apoptosis of neurodegenerative cells or cancer cells." (PMID 31395805, 2019). "Thus, due to the correlation of USF2 and CDK5 in partially the same cancers, CDK5 seems to be of special interest in the context of USF2 regulation." (PMID 31013770, 2019). "As BIN1 has been proved to play a pivotal role in proliferation, invasion and migration abilities of cancer cells, we then detected whether CDK5 could affect these malignant behaviors by inhibiting the tumor suppressing effect of BIN1." (PMID 31496920, 2019). "CDK5 is known to be critical for tumorigenesis and cancer progression." (PMID 31488827, 2019). "CDK5 participates in actin polymerization, microtubule remodeling, integrin activation, and cellular adhesion, which correlates to its roles in regulating the invasion and motility of cancer cells." (PMID 31395805, 2019). "To date, little is known about the possible role of Cdk5 as a cancer biomarker." (PMID 31614664, 2019). "IHC analysis of CDK5 and p21 on cancer tissues after surgery may help to evaluate and predict the outcome of ccRCC patients." (PMID 31311512, 2019). "CDK5 was reported to participate in certain cancer cell migration and invasion." (PMID 31272499, 2019). "Recent evidence found that CDK5-induced G2/M arrest played an important role in cancer progression." (PMID 30621723, 2019). "Consultation of cancer genome repositories such as cBioPortal, the COSMIC database and TumorPortal reveals a variety of other missense mutations within CDK–cyclins in the context of cancer (e.g. R168C in CDK5, R86Q CDK9, R378G in cyclin A2)." (PMID 30185601, 2018). "Interestingly, CDK5 was recently found to play an important role in invadopodia formation and cancer cell invasion, and CDK5 inhibition blocked both these processes." (PMID 28287395, 2017). "The inhibition of Cdk5 can effectively suppress cancer proliferation and metastasis in cancer cells, and can synergize the killing effect of chemotherapeutics and meanwhile reduce its side effects, providing a better strategy for the clinical application of chemotherapeutics." (PMID 28288624, 2017). "Elevated levels of CDK5 have been found in various mouse tumors and human malignant tumors." (PMID 28077789, 2017). "CDK5 was significantly increased in 14 cancers, including liver HCC." (PMID 29312535, 2017). "The level of Cdk5 and its kinase activity are generally dysregulated in various cancer tissues and tumor cell lines, and the dysregulation is linked with DDR, apoptosis, tumorigenesis, EMT, metastasis and other cancerous characteristics via a series of complex mechanisms." (PMID 28288624, 2017). "Glutathione-S-transferase pi 1 (GSTP1) is demonstrated to inhibit Cdk5 activity directly by binding to Cdk5 and dislodging p25/p35, and indirectly by suppressing oxidative stress-induced Cdk5 hyperactivation in neuronal and cancer cells." (PMID 28288624, 2017). "CDK5, kinase protein, may be transferred between cancer cells or be secreted to modulate tumor microenvironment and angiogenesis by tumor-associated exosomes." (PMID 28530703, 2017). "All the studies provide potential targets of Cdk5-relating pathways for cancer treatment." (PMID 28288624, 2017). "Moreover, compared with cirrhotic and para-carcinoma tissues in the liver, CDK5 expression was increased in HCC (P<0.001)." (PMID 29312535, 2017).
cancer (continued). "In addition to western blot analysis, immunohistochemistry has also been performed to detect expression of CDK5 in cancer tissue." (PMID 26860827, 2016). "This study not only further elucidates the precise role of CDK5 in the pathogenesis of CRC but also provides new insight into the biological basis of cancer progression and may help to contribute to more effective therapeutic strategies for CRC." (PMID 27735944, 2016). "The regulative mechanism of CDK5 in several cancers was investigated." (PMID 26860827, 2016). "In a word, the role of CDK5 in cancer is attracting increasing attention." (PMID 26860827, 2016). "To date, the expression of CDK5 was investigated in several cancers." (PMID 26860827, 2016). "In addition to the expression of CDK5 in cancer tissues, the relationship between CDK5 and pathological parameters has been paid more and more attention to." (PMID 26860827, 2016). "Recently, CDK5 has been demonstrated to be involved in pancreatic, lung, and prostate cancer." (PMID 27438154, 2016). "Indeed, NOXA is constitutively expressed in cancer cells, and many cancers exhibit increased CDK5 activity that is important for tumor growth and survival of thyroid and neuroendocrine cancers." (PMID 26791262, 2016). "CDK5 is a member of CDKs and the investigation of CDK5 in cancer is increasing." (PMID 26860827, 2016). "Besides, knocking down CDK5 significantly repressed several key carcinoma molecular pathways, with the ERK5 signaling pathway mostly inhibited (z-score: −3.74)." (PMID 27735944, 2016). "We propose that CDK5 regulation of CRMP2A could contribute to cancer initiation and progression, and this is supported by recent evidence implicating CDK5 activity in taxol-induced cancer metastasis." (PMID 26555036, 2015). "Suppression of the nestin/CDK5 complex reduces proliferation, migration and metastasis in cancer." (PMID 25371063, 2015). "CDK5 is also involved in cell cycle of cancer by inactivating pRB." (PMID 26205145, 2015). "When expression of CDK5 was measured by immunohistochemical staining of a tissue microarray with more than 200 cases of primary cancer, we found that patients with high CDK5 expression, particularly expression in the cytoplasm have poor overall survival using Kaplan-Meier survival analysis." (PMID 26146988, 2015). "Thus there is an overall elevation in the expression of several mRNAs encoding CDK, cyclins and CKI in proliferating malignant tumors compared to arrested benign MTC, thereby suggesting a role for CDK5 activity in the cell cycle." (PMID 25900242, 2015). "However, activation of CDK5 in cancer induces nestin reorganization, and inhibition of CDK5 reduces tumor growth and metastasis." (PMID 25371063, 2015). "This substrate profile reflects the neuronal focus of CDK5 research and, combined with the lack of cell cycle regulation of its activity, means that CDK5 has generally not been associated with a key role in cancer initiation, progression or therapy." (PMID 26555036, 2015). "Phosphorylation of CRMP2 by CDK5 is associated with altered function in neurons, however the role of phosphorylation of CRMPs by CDK5 in cancer has not yet been studied." (PMID 26555036, 2015). "The aims of our study were to identify high-confidence substrates as biomarkers of CDK5 activity in tissue and use these surrogate marker(s) of CDK5 activity to establish whether CDK5 activity was altered in human carcinoma." (PMID 26555036, 2015). "Together, these studies indicate that inhibition of CDK5, alone or in combination with other agents, may provide an effective therapeutic strategy for these and other cancer types." (PMID 24841903, 2014). "These lines of evidence suggest that Cdk5 might involve RA-related effects in cancer cells, such as differentiation and apoptosis." (PMID 23304206, 2012).